CD209 (CD209 molecule)
Diseases named in the same sentence as CD209 in open-access papers (continued):
Sharing a sentence is not in itself a finding about the gene and the disease.
COVID-19 (continued). "Our work provides a prioritised list of host targets potentially exploited by SARS-CoV-2 and is a precursor for further research on CD209 and FAS as therapeutically tractable targets for COVID-19." (PMID 34402426, 2021). "We also observed their association with the variation of immune cell activation in upper airway cells of COVID-19 ARIs that high expression of ACE2 and CD209 was only found in the T/Mø activated cells." (PMID 34502134, 2021). "Therefore, the interaction of CD209 and DCs with neutrophils and T cells may play an important role in mediating cytokine storm coupled with limited anti-viral capability, which are keys in COVID-19 pathogenesis." (PMID 34502134, 2021). "Interstitial macrophages are a dominant target of viral takeover, inflammation, and destruction in COVID-19 initiation, and use DC-SIGN/CD209, but not ACE2, for entry." (PMID 38597954, 2024). "In response to the first published GWAS of COVID-19, we reported findings that link the ABO signal with a number of clinically actionable targets including coagulation factors (von Willebrand factor [vWF], and Factor VIII [F8]), IL-6, and CD209/DC-SIGN." (PMID 34402426, 2021). "Furthermore, pDCs showed a notable increase in CD209 in BALF with accompanying depletion in sera in mild, but not severe, cases, and therefore chemokine homing ligands would reflect the migration changes of pDC from blood to lung in mild and severe COVID-19." (PMID 36851285, 2023).
melanoma (20 papers, 2006 to 2025). A malignant, usually aggressive tumor composed of atypical, neoplastic melanocytes. "CD209 can regulate dendritic cell trafficking and transient T-cell binding; however, its role in melanoma remains unexplored." (PMID 37716991, 2023). "Our study also revealed that DPG could increase miR-4443 and miR-3620 expression in melanoma cells, which are predicted to target the NF-kB post-transcriptional genes, CD209 and TNC, respectively." (PMID 35806253, 2022). "By contrast, melanoma tissues contained a novel CD11c+CD209− subset, maybe representing incoming proinflammatory macrophages, and CD11c+CD209+ mixed cells." (PMID 34439098, 2021). "Our data from the spatial analysis showed that immunosuppressive markers like CD163, CD209, and PDL1 were upregulated in the SLN (+) and SLN (−) of melanoma patients, which were mostly expressed on myeloid cells." (PMID 39062552, 2024). "We first analyzed macrophage subsets in cryopreserved samples, using triple-color labeling with CD11c, CD209, and CD163, to quantify cells with macrophage morphology in normal skin, skin melanoma metastases, and primary melanoma tumors (non-metastasizing and metastasizing)." (PMID 34439098, 2021).
tuberculosis (20 papers, 2008 to 2025). A chronic, recurrent infection caused by the bacterium Mycobacterium tuberculosis. "Previous studies have shown that polymorphisms in the promoter region of CD209 are associated with susceptibility to several infectious diseases including tuberculosis." (PMID 35703715, 2022). "The association between CD209 promoter polymorphisms (-336A/G, -871A/G) and tuberculosis (TB) risk has been widely reported, but results of previous studies remain controversial and ambiguous." (PMID 22911807, 2012). "Although the CD209 -871 SNP was found to be the polymorphism most significantly associated with tuberculosis susceptibility in the South African Cape Coloureds, Barreiro and colleagues found that this SNP is not polymorphic in other African countries." (PMID 18167547, 2008). "The present study investigates the role of the CD209 -336A/G variant in susceptibility to tuberculosis in a large sample of individuals from sub-Saharan Africa." (PMID 18167547, 2008). "For the CD209 -336A/G SNP, however, an overall genotypic association with clinical tuberculosis was observed for this cohort (3x2χ2 = 7.79, P = 0.020)." (PMID 18167547, 2008). "Patients homozygous for the CD209 -336GG allele were associated with 2.4-fold protection against cavitory tuberculosis disease (n = 557, Pearson's 2×2 χ2 = 17.34, P = 0.00003, odds ratio = 0.42, 95%CI 0.27–0.65, PBonferroni corrected = 1.19×10−4)." (PMID 18167547, 2008). "This study finds that the CD209 -336G variant allele is associated with significant protection against tuberculosis in individuals from sub-Saharan Africa and, furthermore, cases with -336GG were significantly less likely to develop tuberculosis-induced lung cavitation." (PMID 18167547, 2008). "However, a significant association was obtained between CD209 -336GG genotype status and lung cavitation in tuberculosis patients." (PMID 18167547, 2008). "CD209 may suppress Toll-like receptor signaling, thereby influencing the Th1/Th2 (proinflammatory/anti-inflammatory) balance and causing M. tuberculosis-induced immune suppression, which may be crucial to tuberculosis disease progression." (PMID 40458711, 2025). "Through differential gene expression analysis, clustering, and enrichment analysis, we identified 13 key biomarkers, including CCL2, SLC11A1, CD209, HLA-DQA1, and TIRAP, which are strongly associated with immune responses in tuberculosis." (PMID 40565607, 2025). "In contrast, the upregulated genes in perirenal adipose tissue of Mirandesa cattle, such as CD209 and MT1E, suggest adaptations related to tuberculosis susceptibility and postpartum oxidative stress, respectively." (PMID 39333243, 2024). "The CD209 -871A/G and -336A/G SNPs were initially genotyped in 329 tuberculosis cases and 327 control individuals from The Gambia (study group A)." (PMID 18167547, 2008). "Here we report studies of the CD209 -336A/G SNP in multiple tuberculosis case control groups based in The Gambia, Republic of Guinea, Guinea-Bissau, and Malawi." (PMID 18167547, 2008). "A total of 2,176 individuals enrolled in tuberculosis case-control studies from four sub-Saharan Africa countries were genotyped for the CD209 -336A/G SNP (rs4804803)." (PMID 18167547, 2008). "Although polymorphisms located in the promoter region of CD209 are widely associated with the severity of various infectious diseases, including tuberculosis, such association has not yet been reported in leprosy." (PMID 35703715, 2022).
ZIKV infection (19 papers, 2016 to 2025). "Cell surface molecules of potential importance for ZIKV infection include the C-type lectin receptors CD209 (DC-SIGN), CLEC5a and mannose receptor (MR) and the phosphatidyl serine receptors T-cell immunoglobulin and mucin domain (TIM)-1 and TAM receptors Tyro3 and AXL42–45." (PMID 31289325, 2019). "Previous studies have shown that AXL and CD209 are ZIKV receptors, and in skin cells, AXL is much more efficient than CD209, TYRO3, and TIM in promoting ZIKV infection (24, 26, 52, –, 54)." (PMID 39570015, 2024).
colorectal cancer (13 papers, 2007 to 2025). A primary or metastatic malignant neoplasm that affects the colon or rectum. "In one study, CD209 on immature dendritic cells was demonstrated to adhere to colorectal cancer cells through the recognition of LewisX and LewisY antigens." (PMID 38593053, 2024). "The data from the present study showed that the addition of fluorine encourages much greater adsorption of CD209 and thus could provide an eloquent and facile strategy for targeting colorectal cancers." (PMID 38593053, 2024). "Several studies have focused on the CD209-positive DCs in cancer tissue, such as cutaneous squamous cell carcinoma, oral squamous cell carcinoma, renal cell carcinoma, prostate intraductal carcinoma, breast cancer, hepatocellular carcinoma and colorectal cancer." (PMID 39684473, 2024). "Additionally, they show how anti-inflammatory protein CD209 is more highly adsorbed to fluorinated polymers and discuss how this may be useful as a biologically tuned microbicide or be a beneficial way for naturally targeting gene-based theranostics toward colorectal cancers." (PMID 38593053, 2024).
breast carcinoma (10 papers, 2016 to 2025). "The aim of the present study was to investigate the density of DCs expressing CD1a, CD83, CD123, DC-LAMP3 (CD208) and DC-SIGN (CD209) in breast cancers." (PMID 33919875, 2021). "This study aimed to investigate the density of DCs expressing CD1a, CD83, CD123, DC-LAMP3 (CD208) and DC-SIGN (CD209) in breast cancer." (PMID 33919875, 2021). "In breast cancer, CD209 may influence the efficacy of ICIs by modulating DCs function." (PMID 40612672, 2025). "LGALS3BP inhibits the differentiation of monocyte-derived fibrocytes through CD209/SIGN-R1 in mouse spleen and is secreted from breast cancer for metastasis." (PMID 34646273, 2021). "CD209, CD163, CSF1, and MMD were related to M2 macrophage proportions in cutaneous melanoma, breast carcinoma, head and neck squamous cell carcinoma, hepatocellular carcinoma, prostate cancer, renal cancer, and lung adenocarcinoma." (PMID 33828973, 2021). "Among these, 34 hotspot mutations such as CD209 R129 missense (4.0 %) in bladder cancer, MAGI1 Q421 insertion (0.8 %) and NR1H2 Q175 insertion (1.8 %) in breast cancer were not well investigated based on previous studies and are potentially novel targets." (PMID 27356755, 2016).
colon carcinoma (8 papers, 2010 to 2025). "The functional role of the soluble CD209 form and the mechanism of its secretion remain largely unknown, although recent studies have linked changes in its serum level to non-Hodgkin lymphoma and colon cancer and proposed that sDC-SIGN could enhance cytomegalovirus infection." (PMID 35594287, 2022).
autoimmune disease (7 papers, 2014 to 2025). A disorder resulting from loss of function or tissue destruction of an organ or multiple organs, arising from humoral or cellular immune responses of the individual to their own tissue constituents. "Interestingly, the migratory capacity of CD209+/CD14+ dendritic cells has been shown to be significantly inhibited by a JAK/STAT pathway inhibitor (tofacitinib) used in the treatment of various autoimmune diseases." (PMID 38275392, 2023).
gastric cancer (7 papers, 2017 to 2025). A primary or metastatic malignant neoplasm involving the stomach. "Furthermore, results from Protein Atlas database validate immune molecules including CD86, CD209, C3AR1, CLEC4D, CLEC7A and CYSLTR2 are positive in gastric cancer cells." (PMID 29152078, 2017). "Based on immunohistochemical staining of DC‐SIGN (hereafter DCsign: DC‐specific ICAM‐3‐grabbing nonintegrin; CD209)‐positive cells, our group recently demonstrated morphological differences between the sentinel and non‐sentinel nodes of early gastric cancer patients without metastasis." (PMID 40151162, 2025).
rheumatoid arthritis (7 papers, 2013 to 2025). A chronic, systemic autoimmune disorder characterized by inflammation in the synovial membranes and articular surfaces. "Certain genetic traits increase the likelihood of developing rheumatoid arthritis (RA); nevertheless, the association between RA and polymorphisms in the CD209 gene is ambiguous." (PMID 41458034, 2025). "Several chronic inflammatory diseases, such as colitis, Crohn's disease, Kawasaki disease, and rheumatoid arthritis (RA), have been reported to be significantly associated with CD206, CD209, and Dectin-1." (PMID 28377641, 2017). "This CD209/CD14+ DC population is present in the circulation of Healthy Control (HC), with increased frequency in Rheumatoid Arthritis (RA) and Psoriatic arthritic (PsA) patients." (PMID 35095831, 2021).
allergic disease (6 papers, 2016 to 2025). An immune response that occurs following re-exposure to an innocuous antigen, and that requires the presence of existing antibodies against that antigen. "Among foods, it has been reported that CD209 preferentially binds proteins derived from allergenic foods, such as peanut or walnut, in comparison to food less commonly associated with allergy, such as pine nuts or chickpeas." (PMID 33944900, 2021). "Because CD209 promotes the uptake of food antigen for processing and presentation by APCs, while CD23 captures (food antigen–specific) IgE, we speculate that these separate DC subsets perform distinct roles in IgE-mediated allergy." (PMID 33944900, 2021).
leprosy (6 papers, 2008 to 2025). Leprosy is a chronic infectious disease affecting primarily the skin and peripheral nervous system. "No other studies in the Brazilian population have investigated the association between CD209 SNVs and the clinical forms of leprosy." (PMID 35703715, 2022). "In summary, our results indicate, for the first time, an association between rs735240 and the CD209 gene and leprosy immunological dichotomy, as has been observed in other infectious diseases." (PMID 35703715, 2022). "Accumulating CD209+ Mφ in leprosy skin lesions have been associated with mycobacterial persistence." (PMID 18827881, 2008). "Carriers of the A allele showed reduced expression of CD209 and TGF-β1 in leprosy lesions in comparison with individuals with GG genotype, in addition to a higher response to the Mitsuda test." (PMID 35703715, 2022). "By contrast, in the progressive, lepromatous (L-lep) form of leprosy, patient lesions are characterized by disorganized granulomas containing MΦ which co-express CD209 and CD163 but lack antimicrobial activity." (PMID 27532668, 2016). "The presence of IFN-γ, JAG1-expressing EC and CD209+CD163neg MΦ in the self-limited form of leprosy suggests that the IFN-γ-JAG1-antimicrobial MΦ differentiation pathway contributes to host defense at the site of disease in leprosy." (PMID 27532668, 2016). "CD14+CD209+CD163+ triple positive cells are also described in the human dermis, in a murine leprosy model, and in the decidua of early human pregnancy." (PMID 36291154, 2022). "Although the findings for the expression levels of CD209 and TGF-β1 in leprosy lesions and DC cultures are in accordance, the data obtained in vitro included few patients and only two individuals with the GG genotype for rs735240, therefore requiring further confirmation." (PMID 35703715, 2022). "In the self-limited, tuberculoid (T-lep) form of leprosy, disease lesions contain well-organized granulomas with M1 MΦ, expressing the MΦ marker CD209, but negative for the haptoglobin receptor CD163, yet armed with antimicrobial effector function." (PMID 27532668, 2016).
parasitemia (6 papers, 2018 to 2022). "Specifically, individuals with the homozygous mutant allele (rs4804803G/G) for the CD209 gene have a significantly greater susceptibility to malaria, and presented with higher mean parasitemia." (PMID 31979279, 2020). "Malaria patients with the CD209 gene wild type variants were much younger and had a lower mean parasitemia compared to patients with the mutant variant (older in age and a higher mean parasitemia)." (PMID 31979279, 2020). "The monocytes which were induced into senescence using D-galactose exhibit pro-inflammatory activity and increased DC-SIGN (CD209) expression, which indicates an increased propensity to viral, bacterial, and parasitic infection." (PMID 34072224, 2021). "The fact that this is not the case confirms our suspicion that higher parasitemia among malaria patients is hinged on the preponderance of the CD209 mutant G allele, mediating a poor antigen presentation and an unmitigated disaster in the immune response." (PMID 31979279, 2020). "Considering the paucity of available data, what are the roles of CD209, CD28 and STAT6 gene polymorphisms, either individually or in combination, with malaria infection among children, and how are they associated with markers of disease severity (age, anemia and parasitemia)?" (PMID 31979279, 2020).
Arthritis (5 papers, 2013 to 2020). Inflammation of a joint. "For the therapeutic target, CD11c+, CD206+, CD209+, and Dectin-1 can be more reliable candidates for BD arthritis." (PMID 28377641, 2017). "CD11c+ and CD209+ cells were significantly decreased after improvement of arthritis in BD patients." (PMID 28377641, 2017). "Therefore, in this study, the expression of CD206, CD209, and Dectin-1 was analyzed and compared between active and inactive BD patients with arthritis." (PMID 28377641, 2017). "We also found that the ST sublining of undifferentiated and established arthritis patients showed a high percentage of CD163+ CD209low/- whereas healthy controls exhibited a high percentage of CD163+ CD209+, suggesting they may be resident macrophages with a potential anti-inflammatory function." (PMID 33679701, 2020).
atherosclerosis (5 papers, 2015 to 2023). A disease characterized by the build-up of fatty material and calcium deposition in the arterial wall resulting in partial or complete occlusion of the arterial lumen. "A previous study found significant increases in the level of immature DCs (with CD209 as a marker) in the course of plaque progression in patients with atherosclerosis, especially in those with unstable atherosclerotic lesions." (PMID 36860279, 2023). "Immunostaining with these markers showed a significantly higher cells number of immature as well as mature mDCs in femoralis plaques compared to arteries without signs of atherosclerosis: 16 versus 8 CD209+ mDCs/0.1 mm2 (P = 0.012) and 19 versus 5 CD83+ mDCs/0.1 mm2 (P = 0.034)." (PMID 25960616, 2015).
Crohn disease (5 papers, 2007 to 2025). A gastrointestinal disorder characterized by chronic inflammation involving all layers of the intestinal wall, noncaseating granulomas affecting the intestinal wall and regional lymph nodes, and transmural fibrosis. "CD209+CD14+ cells were significantly increased in the lesion of lamina propria of Crohn's disease." (PMID 28377641, 2017). "A functional variant in the CD209 gene, rs4804803, does not seem to be influencing Crohn's disease susceptibility." (PMID 18070336, 2007). "CD209 was reported in secondary progressive multiple sclerosis and Crohn's disease; however, the correlation was not studied in BD." (PMID 28377641, 2017).
cytomegalovirus infection (5 papers, 2012 to 2022). A herpesvirus infection caused by Cytomegalovirus. "Interestingly, the CDs that expressed significantly higher levels of CD209 were also more susceptible to cytomegalovirus infection." (PMID 34970264, 2021).
Granuloma (5 papers, 2010 to 2022). A compact, organized collection of mature mononuclear phagocytes, which may be but is not necessarily accompanied by accessory features such as necrosis. "The presence of severe granulomas was associated with a profile of up-regulation of innate immunity-related genes such as complement factors C1q and C6, mannose binding protein, lysozyme C, C-type lectin receptor, CD209, Cathepsin D, CD63, LECT-2, CC chemokine and metallothionein." (PMID 20507624, 2010). "We also identified γδ T cells (0.1% ± 0.3), CD209+ DCs (0.2% ± 0.6) and Treg cells (1.0% ± 1.7), highlighting the capability of our approach to enumerate low-abundance cell populations that are suggested to play a key role in granuloma pathology." (PMID 35058616, 2022). "In combination, CD209+ macrophages and the Th1 inflammatory response are critical to the clearance of mycobacterium from the host, whereas tissue-like macrophages are critical to sustaining granulomas, thus preventing the spread of disease within the host in vivo." (PMID 31167948, 2019).